TRPV1 (transient receptor potential cation channel subfamily V member 1)
Diseases named in the same sentence as TRPV1 in open-access papers (continued):
Sharing a sentence is not in itself a finding about the gene and the disease.
breast carcinoma (continued). "The evidence for a differential TRPV1 expression has been demonstrated in a variety of tumor types, including human breast cancer cell lines." (PMID 37755210, 2023). "Taken together, the anti-tumoral properties of TRPV1 can be further enhanced via chemotherapeutic drugs in breast cancer, such as doxorubicin and cisplatin." (PMID 37755210, 2023). "An example of the changes in TRP expression is the upregulation of TRPV1 and TRPV2 ion channels at Golgi apparatus, endoplasmic reticulum, and surrounding structures in breast cancer patients associated with worse survival." (PMID 35685622, 2022). "In BRCA, we compared TRPV1 expression levels among breast cancer subtypes defined by the PAM50 assay." (PMID 36304985, 2022). "The TRPV1 antagonist melatonin increased the pro-apoptotic efficacy of doxorubicin in human breast cancer MCF-7 cells." (PMID 35402237, 2022). "TRPV1 is also activated in a variety of cancers, such as tongue squamous cell cancer, pancreatic cancer, breast cancer, and prostate cancer." (PMID 36304985, 2022). "Sevoflurane, but not propofol, at clinically relevant concentrations and durations: increased survival of breast cancer cells in vitrono effect on cell proliferation, migration or TRPV1 expression." (PMID 36612205, 2022). "For example, TRPV1 upregulation was verified in human pancreatic cancer, prostate carcinoma, and breast cancer." (PMID 35402237, 2022). "The toxicity of DDP was increased by ALA-mediated TRPV1-channel activation in breast cancer MCF-7 cells." (PMID 35402237, 2022). "TRPV1 is expressed at high levels in human primary brain tumors, pancreatic cancer squamous cell carcinoma of the tongue, prostate carcinoma and breast cancer." (PMID 35402237, 2022). "Other studies also reported the role of TRPV1 levels in colorectal cancer progression, gastric cancer, and breast carcinoma." (PMID 35685622, 2022). "TRPV1 overexpression was also found to promote apoptosis of human melanoma A2058 and A375 cells and breast cancer MCF-7 cells." (PMID 35402237, 2022). "Applying TRPV1 agonist capsaicin in breast cancer and glioblastoma contributes to cell apoptosis due to mitochondria Ca2+ overloading-increased ROS level." (PMID 36045706, 2021). "TRPV1 was also activated by 5-fluorouracil, inducing apoptosis; however, 5-fluorouracil toxicity was downregulated by the TRPV1-channel inhibitor Hypericum perforatum in breast cancer MCF-7 cells." (PMID 34131404, 2021). "Transient receptor potential cation channel subfamily V member 1 (TRPV1), also named “capsaicin receptor”, was recently reported to be aberrantly expressed in many tumor types such as breast cancer, skin tumors, or colon cancer." (PMID 34834237, 2021). "The upregulation of TRPV1 in high-grade prostate and breast cancer samples correlates with the tumor grade, while downregulation of TRPV1 expression is associated with the progression of urothelial cancers." (PMID 34356643, 2021). "TRPV1 has been shown to be significantly upregulated in breast cancer, and both TRPV1 agonists and antagonists have been shown to have anti-cancer effects." (PMID 34067971, 2021). "In 2016, Pecze and co-workers demonstrated that the ectopic expression of TRPV1 in human breast cancer MCF-7 cells led to apoptosis." (PMID 34131404, 2021). "Although additional investigation of mechanisms is needed in relation to ER, PR, and TRPV1, tramadol can be considered to act specifically in breast cancer with ER or PR positive status and regulate TRPV1." (PMID 34764420, 2021). "TRPV1 activity, which is inhibited by melatonin, prevents breast cancer cells from doxorubicin-induced cell death." (PMID 36045706, 2021). "For example, TRPV1 is expressed in several breast cancer cell lines, peculiarly is found to inhibit cellular proliferation in triple-negative breast cancer." (PMID 34572262, 2021). "Elevated TRPV1 expression has also been verified in squamous cell carcinoma of the human tongue, prostate carcinoma, and breast cancer 66-68." (PMID 34131404, 2021).
breast carcinoma (continued). "This suggests that a high baseline cytosolic Ca2+ concentration is needed to support breast cancer cell survival and growth, although excessive activation of TRPV1 by exogenous agonists leads to cancer cell apoptosis." (PMID 32993507, 2020). "The anti-proliferative effect of NaHS was rescued by preventing TRPV1-induced extracellular Ca2+ entry wither with capsazepine or KB-R 7943, as recently reported in leukemia, breast cancer, cervical carcinoma cell lines." (PMID 33187307, 2020). "Despite its primarily expressed location, functional expression of TRPV1 was also proved in several cancers such as breast cancer 15, endometrial cancer 16, bladder cancer 17, colorectal cancer 18, and prostate cancer 19, among others." (PMID 32913462, 2020). "To elucidate the mechanism of sevoflurane on breast cancer cell viability, we studied the role of cell membrane Ca2+ channel TRPV1 activation on cell survival." (PMID 32993507, 2020). "TRPV1 was expressed at low levels among breast cancer, colorectal cancer, kidney cancer, liver cancer, melanoma, and brain cancer." (PMID 32913462, 2020). "Specifically, transient receptor potential vanilloid 1 (TRPV1) is a Ca2+ transport protein expressed in high levels in various aggressive breast cancer cell lines compared to normal breast epithelial cells." (PMID 32993507, 2020). "Sevoflurane, but not propofol, at clinically relevant concentrations and durations increased the survival of breast cancer cells partially through the activation of TRPV1 Ca2+ channels." (PMID 32993507, 2020). "On the contrary, TRPV1 was found overexpressed in prostate and breast cancers, therefore its inhibition decreased cancer cell survival." (PMID 32575381, 2020). "Ten μM capsaicin was found to stimulate TRPV1 and induce long-lasting elevations in in MCF-7 breast cancer cells, while the effect of TRPV1 stimulation on prostate cancer is more controversial." (PMID 33187307, 2020). "Functional expression of TRPV1 was demonstrated in several tumor types including human breast cancer cell lines (MCF-7 and BT-20), human papillary thyroid carcinoma BCPAP cells, prostate cancer (LNCaP and PC-3), urothelial cancer cells, and glioma." (PMID 31681615, 2019). "TRPV—It has recently been shown that 5-FU induced breast cancer cell death was up-regulated by TRPV1 activation: Ca2+ entry through TRPV1 is able to decrease chemoresistance." (PMID 30884858, 2019). "TRPV1 is expressed in human breast cancer MCF-7 and BT-20 cells, prostate cancer derived LNCaP and PC-3 cells, and Benign Prostate Hyperplasia (BPH) tissue expresses TRPV1." (PMID 27472308, 2016). "TRPV-1 is expressed in various types of cancers and capsaicin-induced cell death of MCF-7 breast cancer cell line has been reported to be dependent on TRPV-1 expression levels." (PMID 26888607, 2016). "Consequently, it can be deduced that ‘activation of TRPV1 can inhibit breast cancer cell proliferation’, and the conclusion that ‘further development and application of TRPV1 agonists can be anti-tumour in terms of inhibiting proliferation’." (PMID 40078961, 2025). "Thus, further studies are needed to add more clinical samples for careful evaluation of TRPV1 expression in different subtypes of breast cancer." (PMID 38734935, 2024). "TRPV1 is a crucial factor in the occurrence and development of breast cancer." (PMID 38734935, 2024). "Additionally, TRPV1’s potential as a biomarker and therapeutic target in breast cancer has been elucidated, highlighting its role in inhibiting tumor growth and inducing apoptosis." (PMID 39407657, 2024). "Likewise, TRPV1 is expressed in breast carcinoma tissues, offering potential insights for therapeutic strategies by targeting TRPV1 activation with capsaicin." (PMID 39407657, 2024). "TRPV1 activation in tumor-bearing mice (breast carcinoma) decreases IFN-γ and increases IL-6." (PMID 37371563, 2023).
breast carcinoma (continued). "Similarly, activation of TRPV1-positive sensory nerve fibers was shown to enhance anti-tumoral immunity in a breast cancer model." (PMID 37371563, 2023). "Interestingly, in the MCF-7 breast cancer cell line, both TRPV1 agonists and antagonists significantly reduce cell growth with yet poorly known mechanisms." (PMID 34356643, 2021). "The expression of TRPV1 is elevated in many cancers, and its overexpression suppresses cell proliferation in intestinal, melanoma, and pancreatic cancers and induces apoptosis in melanoma and breast cancers." (PMID 34131404, 2021). "Additionally, despite its status as a TRPV1 antagonist, capsazepine upregulates proliferation in canine breast cancer cells Another TRPV1 antagonist, AMG9810, enhances proliferation in human keratinocytes and murine skin cancer models." (PMID 32545311, 2020). "In addition, the anticancer activity of selenium via TRPV1 was evaluated in the MCF-7 breast cancer cell line." (PMID 32545311, 2020). "Sevoflurane partially reverses the decrease in survival caused by TRPV1 antagonism suggesting that sevoflurane may enhance breast cancer cell survival through the activation of TRPV1 Ca2+ channels." (PMID 32993507, 2020). "Overexpression of TRPV1 channels in some breast cancer cell lines may contribute to breast cancer cell processes important in tumor progression such as angiogenesis." (PMID 32993507, 2020). "However, some found TRPV1 activation in breast cancer cells (MCF-7) to result in necrotic cell death." (PMID 32545311, 2020). "In breast cancer tissues and cell lines, TRPV1 mRNA is highly overexpressed." (PMID 32887220, 2020). "The presence of TRPV1 in MCF-7 breast carcinoma also has been reported." (PMID 31881661, 2019). "Systemic removal of TRPV1+ neurons in mice increased the number of metastasis of breast cancers." (PMID 28626428, 2017). "Additionally, TRPV1 upregulation has been documented in multiple types of human breast carcinoma compared to healthy tissue, whereas, in murine models, TRPV1 downregulation has been linked to an increased risk of developing colon carcinoma and urothelial carcinoma progression." (PMID 40804975, 2025). "This study aimed to investigate the impact of E2 on TRPV1 expression, hypoxia-inducible factor-1α (HIF-1α), and calcium signaling in MCF-7 breast cancer cells (ERα-positive) and TRPV1-transfected CHO cells (ERα-negative)." (PMID 41303593, 2025). "In human breast cancer, CBD has been reported to inhibit cell growth and induce apoptosis through the activation of both CB2 and TRPV1." (PMID 40870993, 2025). "Within this review, we will assess the existing understanding of how five specific TRP channels (TRPA1, TRPC5, TRPV1, TRPV2, and TRPM2) contribute to the resistance of breast cancer to therapeutic interventions." (PMID 37755210, 2023). "The anti-breast cancer effect of tramadol appears to involve the inhibition of proliferation, induction of apoptosis, and effects on 5-HT2B receptor and TRPV-1 for Michigan Cancer Foundation-7 (MCF-7, breast adenocarcinoma cell)." (PMID 35330383, 2022). "The anti-breast cancer effect of tramadol appears to involve inhibition of proliferation, induction of apoptosis, and effects on 5-HT2B receptor and TRPV-1." (PMID 35330383, 2022). "DDP toxicity in breast cancer MCF-7 cells was increased by alpha-lipoic acid (ALA)-induced TRPV1 channel activation, and this effect was reversed by the TRPV1 blocker capsazepine." (PMID 35402237, 2022). "In breast cancer MCF-7 cells, the toxicity of 5-FU was reduced by the TRPV1-channel inhibitor Hypericum perforatum." (PMID 35402237, 2022). "In human breast cancer MCF-7 cells, doxorubicin treatment activated TRPV1, resulting in increased intracellular Ca2+, which was reversed by the TRPV1 antagonist melatonin." (PMID 34131404, 2021).
breast carcinoma (continued). "TRPV1 and downstream Ca2+ ion signaling get activated in breast cancer MCF7 cells and glioblastoma treated with TRPV1 positive allosteric modulator MRS1477 or capsaicin, respectively, to trigger cell death." (PMID 34572262, 2021). "For instance, cannabidiol prevented the proliferation of human breast cancer MBA-MD-231 cells through the activation of cannabinoid receptor type 2 (CB2) and TRPV1 to elevate intracellular Ca2+ and ROS generation and induce apoptosis." (PMID 34131404, 2021). "The findings of a recent study by Erin were in line with this view, as they showed the activation of TRPV1 by capsaicin downregulated the expression of TNF-a, IL-6, and IL-10 and suppressed lung metastasis in a breast cancer metastasis mouse model." (PMID 34131404, 2021). "In this regard, activation of the TRPV1 channel has been shown to enhance the cytotoxic effects of 5-FU, cisplatin, and doxorubicin in MCF-7 breast cancer cells." (PMID 32575381, 2020). "Immunocytochemical staining demonstrated TRPV1 protein expression in SUM149PT cells, a model of triple-negative (PR−, ER−, HER2−) breast cancer." (PMID 32887220, 2020). "Interestingly, PI3K modifies the channel activity of other members of the TRP family, such as TRPV1 in endothelial cells and neurons and TRPC1 in breast cancer cells." (PMID 38564162, 2024). "Moreover, TRPV1 activation increased the cytotoxicity and apoptosis induced by 5-Fluorouracil (5-FU) in MCF-7 human breast cancer cells." (PMID 39407657, 2024). "TRPV1 plays an important role in breast cancer development and treatment; however, a comprehensive review on the relationship between TRPV1 and TNBC is lacking." (PMID 38734935, 2024). "Several studies have evaluated TRPV1 without significant expression differences among breast cancer subtypes." (PMID 38734935, 2024). "first demonstrated that TRPV1+ PSNs do not affect the growth of primary mammary tumors but inhibit the formation of cardiac and pulmonary metastases, via a mechanism involving SP and its receptor neurokinin-1 receptor (NK-1R)." (PMID 38433844, 2024). "For example, in human breast cancer “non-classical” TRPV1 expression (in the Golgi area) heralds poor prognosis compared to “classical” expression in the cell membrane." (PMID 37371563, 2023). "The antitumor effects of CBD were shown to depend on TRPV1 in human neuroblastoma, cervical, lung, and breast cancer, and colon adenocarcinoma, but not in glioblastoma, human leukemia, or murine thymoma." (PMID 35337163, 2022). "In breast cancer, bladder cancer, and low-grade glioma, TRPV1 expression was more inferior in invasive than in noninvasive subtypes." (PMID 36304985, 2022). "For example, viability and proliferation in the MDA-MB-231 cell line (breast cancer) was reported to be independent of TRPV1, when cells were cultured in serum-free conditions." (PMID 35337163, 2022). "Though TRPV1, TRPV4, and TRPV6 all mediate calcium fluxes in breast cancer cells, their unique and even opposite functions in breast cancer progression suggest a complicated network of calcium signaling in modulation of tumor cell functions, which requires further efforts to elucidate." (PMID 32211326, 2020). "So far, TRPV1, TRPV4 and TPRV6 have been well-studied in breast cancers progression." (PMID 32211326, 2020). "Similarly, the expression of TRPV1 and TRV4 is elevated in human hepatoblastoma and breast cancer cells, respectively, and the expression level of TRPV6 correlates with tumor progression in prostate, thyroid, colon, ovarian, and breast cancers." (PMID 25710007, 2015). "Western blot analysis showed that when kidney cells (HEK-293e found to express TRPV1), alveolar epithelial cells (MLE-12), carcinoma breast cancer cell line (MCF-7) or colon cancer cells (HT-29) are treated with the TRPV1 agonist capsaicin, they accumulate Hsp70, Hsp90 and Hsp27 proteins." (PMID 23468922, 2013).
breast carcinoma (continued). "Recent studies showing that TRPV1 is involved in the cross-talk between cancer and immune cells in the TME and that targeting TRPV1 can effectively increase tumor immune infiltration by suppressing TGF-β signaling in pancreatic and breast cancer models support this hypothesis." (PMID 39152432, 2024). "In keeping with this hypothesis, olvanil, a non-pungent vanilloid agonist that activates TRPV1 more slowly than capsaicin does, was shown to suppress metastasis of breast carcinoma without altering the rate of primary tumor growth." (PMID 37371563, 2023). "Moreover, TRPV1 is a potential negative prognostic marker in breast cancer where TRPV1 expression in the endoplasmic reticulum and Golgi apparatus (and/or the surrounding of these structures) heralds poor prognosis." (PMID 32887395, 2020). "The MCF7 breast cancer cell line, although it expresses endogeneously low levels of TRPV1 receptors, cannot be subjected to necrotic-like procecesses by administration of CAP or RTX, but shows the typical structural changes when TRPV1 is ectopically overexpressed." (PMID 28626428, 2017). "Till now, though not as much as those reported in breast cancer cells and osteoclasts, multiple calcium channels have also been reported to modulate osteoblast proliferation, differentiation, migration and mineralization, including TRPV1, TRPV4, TRPM7, TRPP2, Cav1.2, ORAI1/SOCE, P2X1, and P2X7." (PMID 32211326, 2020). "TRPV1 is a nonselective cation channel that can be activated by different physical and chemical stimuli; it is commonly upregulated in several cancers, including tongue squamous cell cancer, PAAD, breast cancer, and prostate cancer." (PMID 39152432, 2024). "Unlike TRPV1 and TRPV4, TRPV6 has been shown to positively promote breast cancers progression." (PMID 32211326, 2020). "It has been reported that TRPV1 activation via capsaicin together with MRS1477 largely reduces MCF-7 viability, which is not observed in primary breast epithelial cells, indicating TRPV1 is a potential drug target for treating breast cancers without affecting normal cells." (PMID 32211326, 2020).